TLR7 (toll like receptor 7)
Diseases named in the same sentence as TLR7 in open-access papers (continued):
Sharing a sentence is not in itself a finding about the gene and the disease.
tumor (continued). "Intriguingly, stimulation of TLR7/8 signaling with TLR7/8 agonists can subvert tumor-induced immunosuppression in several types of solid cancers and has shown great promise in tumor therapy." (PMID 31849942, 2019). "As TLR7 is an X-linked gene, male mice harboring hemizygous null deletions in TLR7 (TLR7KO) were used to query the role of host TLR7 in R848-mediated tumor response." (PMID 31615993, 2019). "In human papillomavirus (HPV)-positive oropharyngeal cancer, expression of TLR5 and TLR7 correlated with tumor recurrence." (PMID 30976817, 2019). "The anti-tumor activity of this TLR7/8 agonist is enhanced when combined with T cell-targeted immunotherapies in pre-clinical models." (PMID 31511088, 2019). "TLR7-based adjuvants are therapeutically effective in both anti-viral and anti-tumor immune responses." (PMID 31507609, 2019). "Most recently, researchers reported the anti-tumor efficacy of a nanosystem delivering TLR7/8 agonist to target TAMs31, as well as successful reactivation of cytotoxic T cells to eliminate cancer cells by upregulating IL-12 p40 in macrophages." (PMID 31118418, 2019). "Localized TLR7/8 agonism can enhance recruitment and activation of immune cells in tumors and polarize anti-tumor immunity towards a Th1 response." (PMID 31511088, 2019). "Here, the authors show TLR7/8 agonist R848 remodels host and tumour immune responses, promoting survival and attenuating cachexia in murine models of PDAC." (PMID 31615993, 2019). "Recently, it was shown that an agonist against TLR7 can activate NK cells to completely lyse tumor cells." (PMID 29650045, 2018). "A combination of TLR7, 8 and 9 ligands enhanced anti-tumor responses by NK cells and cytotoxic T-cells and reduced MDSC frequency." (PMID 30271756, 2018). "TLR7 in dendritic cells appears to have immunomodulatory and anti-tumor potential, but little is known about the contribution of this receptor in carcinogenesis." (PMID 29416610, 2018). "For example, GTL001 induced strong antigen-specific T cell responses and tumor eradications in a curative strategy when adjuvanted with a TLR7 agonist." (PMID 29739434, 2018). "First, TLR7 activation is an assessed strategy for cancer immunotherapy, where its stimulation leads to the secretion of anti-tumor cytokines." (PMID 29462934, 2018). "Ten patients were enrolled, with two patients receiving a partial response and evidence that the TLR-7 agonist in question helped locally produce cytokines and tumor lymphocytic infiltrate, which in turn created a pro-immunogenic microenvironment." (PMID 29385680, 2018). "Furthermore, the topical application of imiquimod (a TLR7 activator) associated with the intramuscular administration of a DNA vector containing HPV16 E7 fused to calreticulin increased the recruitment of CD8+ T cells to the genital tract in an orthotopic HPV16 E6/E7 syngeneic tumor model." (PMID 30328949, 2018). "The major biologic anti-tumor activity of Imiquimod and R848 is thought to be mediated through agonistic activity towards TLR7, which results in a cell-mediated immune response." (PMID 29422777, 2018). "Imiquimod-stimulated pDCs in mouse models can also directly suppress tumor growth and stimulate apoptosis through TLR7-dependent TNF-related apoptosis-inducing ligand (TRAIL) and granzyme B release." (PMID 29662615, 2018). "In this study, we examined the effects of monotherapy with systemic low-dose resiquimod, a synthesized TLR7 agonist, and examined its combined effects with PD-L1 blockade in two PD-L1 blockade-resistant tumor models (SCCVII and Colon 26)." (PMID 29568358, 2018). "In parallel, TLR7/8 stimulation also induced regulatory genes, such as IL-10, and anti-tumor factors, such as high-mobility group box 1 protein (HMGB1)." (PMID 29190907, 2017). "This research work ventures to delineate the combined effect of vasculature disruption therapy by DMXAA and TLR7/8 agonist gardiquimod on tumor treatment." (PMID 28036266, 2017).
tumor (continued). "Conversely, in A549 cells, TLR7 or TLR8 agonists led to increased tumor cell survival, chemoresistance, and increased anti-apoptotic protein expression, as well as appear to increase MDSCs and reduce CD8+ T cells in mice, promoting tumor growth." (PMID 29190881, 2017). "This article aims to review the anti-tumor activity of TLR7 agonists with a focus on small synthetic molecules." (PMID 28620298, 2017). "Activation of TLR7 can induce Type 1 interferon and inflammatory response, therefore targeting TLR7 is a promising strategy for both antiviral and anti-tumor therapy." (PMID 28620298, 2017). "This modular platform also enables PD-1-targeted delivery of a TLR7/8 agonist to the tumor microenvironment, increasing the proportion of tumor-infiltrating CD8+ T cells and sensitizing tumors to subsequent anti-PD-1." (PMID 29170511, 2017). "This article reviewed the anti-tumor activity and mechanism of TLR7 agonists that are frequently applied in preclinical and clinical investigations, and mainly focused on small synthetic molecules, including imiquimod, resiquimod, gardiquimod, and 852A, etc." (PMID 28620298, 2017). "As previous studies have also reported TLR7 independent activation of apoptosis in imiquimod treated tumour cell lines, we suggest imiquimod induces ER stress via alternative mechanisms." (PMID 27936237, 2016). "Although imiquimod is an agonist of TLR7, previous studies have shown that it can exert effects in tumour cells via TLR7-independent mechanisms." (PMID 27936237, 2016). "The impact of dose-scheduling of a systemically administered TLR7 agonist and RT on the generation of therapeutic anti-tumor immune responses is currently unclear." (PMID 26959743, 2016). "We conclude that VDD promotes tumor growth in the context of Smad3 disruption, potentially through regulation of TLR7 expression and β-catenin activation." (PMID 27456065, 2016). "As a DFTD immunotherapy, imiquimod has potential to activate TLR7 mediated immune responses, while deregulating tumour growth and survival in a direct and targeted manner." (PMID 27936237, 2016). "Tumor-secreted miR-21 and miR-29 act as paracrine agonist of TLRs to bind TLR7 in mouse or TLR8 in human immune cells, and ultimately lead to TLR-mediated tumor metastasis and growth." (PMID 27336891, 2016). "In human studies, the small immunomodulatory molecule imiquimod is a successful immunotherapy, activating anti-tumour immunity via stimulation of toll-like receptor-7 (TLR7) signaling pathways." (PMID 27936237, 2016). "It is possible that the administration of TLR7 agonist needs to be synchronous with the RT-induced changes in the tumor microenvironment such as tumor cell death and release of TAAs and DAMPs to augment successful CD8+ priming." (PMID 26959743, 2016). "Imiquimod exerts these effects in a tumour specific manner, independently of both TLR7 signaling and immune cell function." (PMID 27936237, 2016). "The immunotherapeutic agent imiquimod activates TLR7-dependent immune responses, resulting in anti-tumour cytotoxicity and tumour regression in human cancers." (PMID 27936237, 2016). "Our analyses of VD deprivation (VDD) in in vivo models of liver tumor formation revealed striking three-fold increases in tumor burden in Smad3+/− mice, with a three-fold increase in TLR7 expression compared to controls." (PMID 27456065, 2016). "For instance tumor cells can induce apoptosis in distal skeletal muscles via exosome assembled miR-21, which signals through the Toll-like 7 receptor (TLR7) on myoblasts to promote cell death and cancer cachexia." (PMID 26839565, 2016). "In human studies imiquimod has also been shown to directly modulate tumour cells via activation of apoptotic pathways independently of TLR7." (PMID 27936237, 2016).
tumor (continued). "To determine the functional role of TLR7 and TLR8 we generated TLR7 and TLR8 expressing human PANC1 cancer cells and analyzed the effects of TLR7/8 agonists (R848, resiquimod) in the inflammatory process on tumor cell proliferation and chemoresistance." (PMID 26134824, 2015). "Oral doses of the TLR7 agonist imiquimod generate antitumoral responses in several murine tumor models as MC-26 colon carcinoma, LLC, and RIF-1 sarcoma." (PMID 26042126, 2015). "Identification of TLR7 as a regulatory marker in the CD3 high group indicates an immunosuppressive phenotype of TLR7-expressing tumor." (PMID 26622942, 2015). "Our results showed that conjugating OCT4 protein to the novel TLR7 agonist produced a vaccine which is effective and safe in preventing tumor growth in mice." (PMID 25990580, 2015). "Recently, Loxoribin, a TLR7 agonist, has been shown to be able to shrink the tumor through augmenting the proliferation of CD4+ T cells and lowering the frequency of Tregs, which is mediated by elevated IL-6 level secreted by DCs." (PMID 26683520, 2015). "TLR7/8 agonists therefore seem to be potent adjuvants to radiotherapy, inducing strong local and profound systemic immune responses to tumor antigens released by conventional therapy." (PMID 25609199, 2015). "In the present study, we show that TLR7 activation by Loxoribin induces tumor regression in vivo, and these anti-tumor effects are mediated by promoting CD4+T cell proliferation and reversing Treg-mediated suppression." (PMID 25593198, 2015). "Recent study demonstrated that the inhibition of iNOS activity enhanced the anti-tumor effect of TLR7 agonist in subcutaneous tumor model." (PMID 26496031, 2015). "Taken together, Loxoribin treatment leads to tumor regression, and the underlying mechanism involves modulation of the CD4+T cell proliferation and the suppressive activity of Tregs via DCs in a TLR7-dependent manner." (PMID 25593198, 2015). "Tumor xenograft growth of TLR7 and TLR8 transduced human PANC1 cancer cells in Balb/c nude mice was examined." (PMID 26134824, 2015). "As previous reports had indicated an involvement of TLR signaling in tumorigenesis, we first evaluated the effects of the TLR7/8 agonist on various tumor cell lines." (PMID 25609199, 2015). "TLRs have been implicated to play a significant role in PDA, as our lab has recently shown that TLR7 ligation accelerates pancreatic carcinogenesis and that TLR7 blockade protected against tumor progression." (PMID 26172047, 2015). "To investigate the effects of the TLR7/8 agonist in combination with classical fractionated photon radiotherapy in vivo, we induced tumor homografts by subcutaneous implantation of CT26 tumor fragments in immunocompetent BALB/c mice." (PMID 25609199, 2015). "This IMQ-induced HIF-1α expression also occurred in TLR7/8-negative tumor cells, although it has been reported previously that the ligand-induced activation of TLR7/8 leads to the accumulation of HIF-1α protein in THP-1 human myeloid macrophages." (PMID 24658058, 2014). "Imiquimod activates anti-tumor immunity via Toll-like receptor 7 (TLR7) in macrophage and other immune cells." (PMID 24743316, 2014). "In a cell culture model, TLR7 agonists were found to enhance tumor cell lysis by human gamma delta T cells." (PMID 23451142, 2013). "It has been proposed that the anti-viral and anti-tumor effects of imiquimod in the skin are mediated by activation of TLR7 and/or TLR8 expressed by monocytes, macrophages, and plasmacytoid dendritic cells (pDCs)." (PMID 24146965, 2013). "By contrast, when this antigen preparation was administered together with a TLR7/8 agonist (30 μg/dose) significant inhibition (p, 0.001, ***) of tumor growth, with complete tumor regression was noted." (PMID 24955288, 2012). "In view of the beneficial effect of vaccination in the context of the multi-TLR agonist BGC, we decided to evaluate the effect of a TLR7/8 agonist in our CNS-1 tumor model." (PMID 24955288, 2012).
tumor (continued). "In our CNS-1 model, the TLR7/8 agonist resiquimod showed superior antitumor effects against early tumor growth and remarkably, administration of TLR7/8 agonist alone inhibited tumor growth." (PMID 24955288, 2012). "We administered the TLR7/8 containing vaccine to animals with large (12-14,000 mm3) tumors, starting at 38 days after tumor implantation." (PMID 24955288, 2012). "Remarkably, administration of TLR7/8 agonist alone in the same regimen also inhibited tumor (p, 0.001, ***)." (PMID 24955288, 2012). "For early stage tumors, a complete regression of tumor growth volume was noted, while for large established 38-day old tumors (14,000 mm3 volume), inhibition of tumor growth was noted for the TLR7/8 containing vaccine." (PMID 24955288, 2012). "TLR7 mRNA expression in the SCC tumor center was 15.6±3.70-fold higher than in normal skin (p<0.001) and also significantly higher than in peritumoral tissue (3.37±1.35, p<0.01) and than in the tumor center of BCCs (1.98±0.53, p<0.001)." (PMID 22808251, 2012). "The anti-viral and anti-tumor activity of synthetic TLR7 agonists has been attributed to the induction of cytokines such as IFNα." (PMID 17935622, 2007). "The study also underscores the powerful immune stimulatory capacity of synthetic TLR7 agonists and their potential and demonstrated use in anti-viral and anti-tumor therapies." (PMID 17935622, 2007). "This implies that the TLR7 agonist leads to better activation and maturation of NK cells with higher capacity for cytokine secretion and cytotoxic activity, thus potentially explaining the tumor growth restriction observed for ALDARA-treated mice." (PMID 41597427, 2026). "These nanomotors, formed via self-assembly of iron carbonyl (FeCO)-bridged silane monomers and the TLR7 agonist resiquimod (R848), enable precise targeting of cancer cells under X-ray irradiation, facilitating efficient cargo delivery, tumor cell elimination, and immune activation." (PMID 41142429, 2025). "Notably, a single-dose of IFNα was sufficient to upregulate TLR7 protein expression on type II DCs and the combination of IFNα and topical IMQ-induced TLR7 expression also on type I DCs in the tumor microenvironment." (PMID 39849091, 2025). "We hypothesized that innate immune activation by TLR7/8 activation primes the immune system against tumor neoantigens, thereby mounting tumor-specific T cell responses that contribute to killing primary tumor cells and distal metastases." (PMID 40230629, 2025). "The possibility that the TLR7/8a VLPs may elicit more potent anti-tumor immune responses compared to TLR9a VLPs warrants further investigation in preclinical and clinical trials as a novel immunotherapeutic strategy." (PMID 41249948, 2025). "For example, tumor-secreted miR-21 and miR-29a can act as ligands for the murine TLR7 and human TLR8 receptors on immune cells, triggering a TLR-mediated prometastatic inflammatory response that may ultimately lead to tumor growth and metastasis." (PMID 40244285, 2025). "In fact, in addition to direct effects on differentiation of MDS cells, in vivo TLR7/8-mediated activation of other immune cells could induce cell-mediated immune responses to tumour cells, also contributing to enhance their therapeutic effect." (PMID 40858756, 2025). "TLR4 signaling promotes tumor growth, while TLR7, TLR8, and TLR9 signaling may exert anti-tumor effects." (PMID 40948759, 2025). "However, activation of TLR7/8 in pulmonary neutrophils enhances their phagocytic capacity against tumor cells, thereby effectively inhibiting the progression of lung cancer." (PMID 41293166, 2025). "Taken together these results suggest that the synergy between oral and topical IMQ is based on type I IFN induction in pDCs by oral IMQ, followed by upregulation of TLR7/8 on myeloid cells such as DCs, possibly sensitizing these immune cells to topical TLR7/8 agonist treatment at tumor sites." (PMID 39849091, 2025).
tumor (continued). "This pro-tumour effect of TLR7 is further supported by studies in animal models." (PMID 40336011, 2025). "In particular, the expression of TLR7 was found to be positively correlated with tumor size." (PMID 39857735, 2025). "The ability of TLR7/8 to activate multiple immune pathways makes them attractive targets for immunotherapy, particularly in the context of cancer, where robust immune activation is essential for effective tumor clearance." (PMID 41228373, 2025). "Furthermore, clinical studies are showing promising effects of TLR9 and TLR7 agonists in enhancing the anti-tumor activity in HNSCC." (PMID 38850110, 2024). "In addition, resiquimod of TLR7 agonist or PF‐3512676 of TLR9 agonist were reported to exhibit significant anti-tumor activity in cutaneous lymphomas." (PMID 39054418, 2024). "For example, combining TLR-7 agonists with photoactivatable agents such as indocyanine green to attack tumor cells in mice can significantly inhibit tumor cell migration in mice and provide strong immune memory to prevent cancer recurrence, applicable to various tumor cells." (PMID 39136021, 2024). "Furthermore, the elevation of TLR7 expression on tumor dendritic cells following FluVx therapy is significant." (PMID 38476365, 2024). "Consequently, TLR7 agonists have garnered attention as promising candidates for anti-tumor immunotherapies." (PMID 39346737, 2024). "TLR7 expression on regulatory B cells within the tumor was also reduced following AdjFluVx therapy." (PMID 38476365, 2024). "The anti-HER2 antibody worked selectively to deliver the TLR7 agonist to HER2+ tumor cells." (PMID 39456611, 2024). "TLR7 signaling may also activate dendritic cells, boosting tumor antigen presentation and promoting tumor-targeting CD8+ T cell responses." (PMID 38476365, 2024). "Hence, several clinical trials evaluate the potential of TLR7 or TLR9 agonists in various tumor indications including head and neck cancer, melanoma, and esophageal cancer (NCT04799054, NCT00669292)." (PMID 39575246, 2024). "Moreover, the delivery of another TLR7/8 agonist 3M-052 to TAMs also induces phenotypic changes in TAMs and promotes tumor regression." (PMID 38338674, 2024). "TLR7/8 agonist resiquimod (R848) can regulate tumor immune microenvironment by polarizing M2 macrophages into M1 macrophages and activating DC, further enhancing the immune system’s anti-tumor effect." (PMID 39697556, 2024). "TLR7 downregulation by AdjFluVx may contribute to the maintenance of regulatory B cell populations and IL-10 production within the tumor, encouraging tumor growth." (PMID 38476365, 2024). "Additionally, we demonstrate that TLR7-treated CB-pDCs promote a strong inflammatory environment in co-culture with cells from tumor digests of CRC patients suggesting a potential to recruit and activate effector cells." (PMID 39575246, 2024). "TLR7 agonists can also stimulate these TLR7-expressing tumor cells." (PMID 38709790, 2024). "Indeed, scRNA-seq analysis of the impact of FA-TLR7-1A on the TME suggests that FRβ+ macrophages contribute prominently to tumor growth, and treatment of FRβ+ TAMs/MDSCs with a TLR7 agonist shifts them to a more inflammatory phenotype." (PMID 38384467, 2024). "In addition, the delivery of TLR7/8 agonist (R848)-loaded β-cyclodextrin NPs to TAMs in vivo has been demonstrated in multiple tumor models to promote M2-to-M1 repolarization, leading to the inhibition of tumor growth." (PMID 38338674, 2024). "Thus, TLR7 agonists are promising candidates for anti-tumor immune therapy and imiquimod is indeed an approved treatment for basal cell carcinoma." (PMID 39054418, 2024). "Correlations between TMB and TLR7 expression in tumor types were analyzed by Spearman." (PMID 37362864, 2023). "Finally, this novel nano-preparation can actively deliver TLR7 agonists to tumor tissues, and has the dual functions as an ICB drug and a TLR agonist." (PMID 37049910, 2023).